CASP8 (caspase 8)
Diseases named in the same sentence as CASP8 in open-access papers (continued):
Sharing a sentence is not in itself a finding about the gene and the disease.
non-Hodgkin lymphoma (2 papers, 2013 to 2017). Distinct from Hodgkin lymphoma both morphologically and biologically, non-Hodgkin lymphoma (NHL) is characterized by the absence of Reed-Sternberg cells, can occur at any age, and usually presents as a localized or generalized lymphadenopathy associated with fever and weight loss. "Genetic variants rs3834129 (CTTACT/−) and rs3769821 (T/C) in the promoter region of the CASP8 gene were documented to be associated with multiple solid cancers and non-Hodgkin’s lymphoma (NHL), respectively, despite of some controversies." (PMID 23844036, 2013).
oral cavity tumors (2 papers, 2018 to 2023). "NSD1 mutations were preferentially laryngeal, while almost all CASP8 mutations were in oral cavity tumors." (PMID 37081260, 2023).
ovarian tumor (2 papers, 2017 to 2020). "IHC results also showed that PCBP1 expression was positively correlated with p62 expression (R2 = 0.506) and Caspase-8 expression levels (R2 = 0.447) in ovarian tumor samples, respectively." (PMID 32922440, 2020). "Furthermore, our analyses showed that these two inhibitors synergistically inhibited the survival of ovarian tumor cells via activation of the Caspase 8/XIAP-dependent pathway." (PMID 28134933, 2017).
pancreatitis (2 papers, 2023). Inflammation of the pancreas. "They include DNA damage response and DNA repair genes (ATM, BRCA1, BRCA2, and POLQ), pancreatitis gene (SPINK1) and cell apoptosis gene (CASP8)." (PMID 37234870, 2023).
pheochromocytoma (2 papers, 2015 to 2025). "The epigenetic analysis revealed consistent methylation of HIC1 and CASP8 in pheochromocytomas, which was significantly more frequent in VHL pheochromocytomas compared to sporadic cases, underlying the presence of differing pathophysiological mechanisms between the two types of tumors." (PMID 40558831, 2025). "Also oxaliplatin increased caspase-8 activity in the rat adrenal pheochromocytoma cell line PC12 from the control value of 178.6 ± 29.6 arbitrary units/mg proteins to 415.8 ± 28.7 arbitrary units/mg proteins." (PMID 25761243, 2015).
reovirus infection (2 papers, 2010 to 2025). "In keeping with the function of extrinsic apoptotic signaling in reovirus infection, caspase-8 activation and Bid cleavage are observed in cells infected with reovirus." (PMID 20617182, 2010). "Apoptosis induction after reovirus infection requires caspase-8-mediated cleavage of Bid." (PMID 41042063, 2025). "Although tBid was generated at 36–48 h following reovirus infection of vehicle-treated cells, reovirus failed to efficiently induce activation of Bid in Z-IETD-FMK-treated cells until 48 h post-infection, providing evidence that reovirus evokes cleavage of Bid via caspase-8." (PMID 20617182, 2010).
retinitis pigmentosa (2 papers, 2013 to 2016). Retinitis pigmentosa (RP) is an inherited retinal dystrophy leading to progressive loss of the photoreceptors and retinal pigment epithelium and resulting in blindness usually after several decades. "Given that RIPK1 and CASP8 take part in the defense of homeostasis downstream of many cytokine receptors, it is possible that inflammatory signals such as TNF contribute to the onset and progression of retinitis pigmentosa due to aberrant activation of RIPK1-dependent cell death." (PMID 26960254, 2016).
rhabdomyosarcoma (2 papers, 2014 to 2019). A rare aggressive malignant mesenchymal neoplasm arising from skeletal muscle. "In order to corroborate the role of caspase-8, the rhabdomyosarcoma cell line RH4, which is known to lack caspase-8, was also studied." (PMID 31817469, 2019).
sarcoma (2 papers, 2007 to 2019). A usually aggressive malignant neoplasm of the soft tissue or bone. "The involvement of caspase 8 pathway suggests an autocrine role that dnStat3 transduction may play in apoptosis-bound sarcoma cells." (PMID 17598902, 2007).
spina bifida (2 papers, 2019 to 2020). A congenital neural tube defect in which vertebrae are not fully formed. "Cleaved caspase 3 levels were elevated in encephalocele cases and cleaved caspase 8 levels were higher in spina bifida cases relative to controls." (PMID 32650820, 2020).
T-cell lymphoma (2 papers, 2020 to 2023). "Moreover, analysis of expression profiling data from selected ALCL (GSE19069) and peripheral T-cell lymphoma patients (GSE6338) showed correlated activities of HHEX, CASP8, FOXO3 and BHLHE40, supporting this regulatory connection." (PMID 32922661, 2020).
tongue squamous cell carcinoma (2 papers, 2017 to 2022). A squamous cell carcinoma that arises from the tongue. "EEP inhibited cell viability and induced apoptosis by upregulation of caspase-3, caspase-8, and caspase-9 in human tongue squamous cell carcinoma cell line." (PMID 28167973, 2017).
uterine corpus endometrial carcinoma (2 papers, 2017 to 2019). A endometrial carcinoma (disease) that involves the body of uterus. "Uterine Corpus Endometrial Carcinoma (UCEC) is another cancer where ∼10% cases harbor CASP8 mutations." (PMID 30775178, 2019). "Apart from HNSC, Uterine Corpus Endometrial Carcinoma (UCECs) carried the most numbers of mutations in the CASP8 gene, as was observed upon searching the Genomic Data Commons." (PMID 30775178, 2019).
Zinc deficiency (2 papers, 2023 to 2024). A deficiency of the essential metal Zinc; an essential cofactor for many enzymes. "Consistently, RT-qPCR results showed that zinc deficiency significantly increased the mRNA levels of Bax, Caspase-3, and Caspase-8 in ovaries." (PMID 38807213, 2024). "that TNF-α with zinc deficiency increases Caspase-8 activity and that zinc administration prevents this zinc-deficiency-induced apoptosis supports our results." (PMID 38022538, 2023).
acute liver failure (1 paper, 2012). Rapid deterioration of liver function causing encephalopathy and coagulopathy. "Caspase-8 has been implicated in hepatocyte apoptosis in liver injury, anti-caspase-8 could effectively inhibit apoptosis of Hepa 1-6 cells induced by TNF-α and caspase-8 small interfering RNA prevents mice from acute liver failure." (PMID 22266786, 2012).
acute viral hepatitis (1 paper, 2012). "Fas, TNF-α and TRAIL are important genes in the death receptor-mediated apoptosis signaling pathway in human acute viral hepatitis, and caspase-8 is a key gene involved in this pathway." (PMID 22266786, 2012).
adenomyosis (1 paper, 2017). The growth of endometrial tissue inside the muscular wall of the uterine corpus. "In CESC, EuESC and EESC cells, changes in the expression of caspase-3, Endo-G, caspase-8, GRP78 and Bax showed a positive correlation with the duration of anoxia, particularly for caspase-3, Endo-G and caspase-8 in adenomyosis." (PMID 28406930, 2017).
adenovirus infection (1 paper, 2020). "Caspase-8 cleavage produces a 50-kDa intracellular fragment during cell apoptosis induced by IFN-γ or TNF-α, while cellular ADAM-17 can produce an 80-kDa extracellular fragment of DSG-2 during adenovirus infection." (PMID 32457708, 2020).
adrenal carcinoma (1 paper, 2021). A carcinoma involving a adrenal gland. "Additionally, mRNA levels of CASP8 were higher in adrenal carcinoma in comparison of normal adrenal tissues in one dataset." (PMID 33828176, 2021).
allergic contact dermatitis (1 paper, 2025). An inflammatory skin condition caused by an immune response to direct contact between the skin and an allergen. "Our finding that CASP-8 significantly increases between baseline and 12 months in persistent CMA contradicts with a previous finding in a study on allergic contact dermatitis, where reduced CASP-8 was related to increased severity of allergy." (PMID 40929127, 2025).
anal squamous cell carcinoma (1 paper, 2016). A squamous cell carcinoma (SCC) arising from the anal canal or the anal margin (perianal skin). "In the present study we aimed to investigate the clinical relevance of Plk3 expression and phosphorylation of caspase-8 at T273 in patients with anal squamous cell carcinoma (SSC) treated with 5-fluorouracil and mitomycin C-based chemoradiotherapy (CRT)." (PMID 27462786, 2016).
ANCA-associated vasculitis (1 paper, 2022). "Our study revealed that the activation of caspase-8 in neutrophils can facilitate the development of ANCA-associated vasculitis through the regulation of inflammation and immune response." (PMID 36505410, 2022).
angina pectoris (1 paper, 2022). The symptom of paroxysmal pain consequent to MYOCARDIAL ISCHEMIA usually of distinctive character, location and radiation. "CASP8 is reported to be decreased in patients with stable angina pectoris compared to controls." (PMID 35733129, 2022).
atrial fibrillation (1 paper, 2025). A disorder characterized by an electrocardiographic finding of a supraventricular arrhythmia characterized by the replacement of consistent P waves by rapid oscillations or fibrillatory waves that vary in size, shape and timing and are accompanied by an irregular ventricular response. "CASP8, as the initiator caspase in the death-receptor pathway, was closely related to AS and AF:upregulated CASP8 could increase the recurrence risk of atrial fibrillation, and activating CASP8 gene in smooth muscle cell in apoptosis processes could influence the progression of AS." (PMID 40607061, 2025).
autism spectrum disorder (1 paper, 2022). A spectrum of developmental disorders that includes autism, and Asperger syndrome. "Interestingly, behavioral analysis demonstrates that mice lacking CASP8 show changes reminiscent of autism spectrum disorders (ASD)." (PMID 35493109, 2022).
Babesia infection (1 paper, 2020). "We also analyzed porin functions in relation to both tick blood feeding and Babesia infection and the relationship between porin and porin-related apoptosis genes such as B-cell lymphoma (Bcl), cytochrome complex (Cytc), caspase 2 (Cas2), and caspase 8 (Cas8)." (PMID 32508681, 2020).
bacteremia (1 paper, 2016). "Eight weeks post-reconstitution, mixed chimeric animals were infected with Yersinia pseudotuberculosis (Yp), which causes a rapid and lethal bacteremia in animals with hematopoietic caspase-8 deficiency." (PMID 27737018, 2016).
bacterial meningitis (1 paper, 2023). Inflammation of the membranes surrounding the brain and spinal cord due to a bacterial infection. "The induction of HBMC apoptosis by promoting the expression of active caspase-8 is a mechanism for inducing bacterial meningitis." (PMID 36977062, 2023).
Barrett adenocarcinoma (1 paper, 2013). An adenocarcinoma arising from Barrett metaplastic epithelium in the esophagus. "Similarly to studies in SEG-1 Barrett’s adenocarcinoma cells we observed that telomerase suppression in MDA-MB-231 cells was also associated with up-regulation of genes for FasL, Fas and caspase-8." (PMID 23677713, 2013).
behavior disorder (1 paper, 2023). "Targeted culturomics and mechanisms study further showed that patient-derived F. varium infection caused systemic inflammation and behavior disorder in Notch3R170C/+ mice potentially via induction of caspase-8-dependent noncanonical inflammasome activation in macrophages." (PMID 37684694, 2023).
benign prostatic hyperplasia (1 paper, 2025). A non-cancerous nodular enlargement of the prostate gland. "The treatment of EF ethanol extract in benign prostatic hyperplasia-1 cells inhibits cell viability through caspase-8 and cystatin-3-dependent apoptosis and effectively inhibits the growth of benign prostatic hyperplasia-1 cells." (PMID 39944619, 2025).
bone metastasis (1 paper, 2024). Transfer of a neoplasm from its primary site to bones. "And in the process of bone metastasis, TREX1 and RELA are protective factors, while CASP8 is a risk factor." (PMID 38835789, 2024).
brain glioblastoma (1 paper, 2020). A WHO grade IV malignant astrocytic tumor that arises from the brain, usually the cerebral hemispheres. "Similarly, another study indicated that βT3 induced caspase-8 activity, increased levels of Bid and Bax protein, as well as altered mitochondrial permeability and levels of cytochrome c in lung adenocarcinoma and brain glioblastoma." (PMID 31963885, 2020).
brain inflammation (1 paper, 2015). "Altogether, our results strongly suggest an anti-inflammatory role of caspase-8 in microglia-mediated brain inflammation." (PMID 26405176, 2015).
bronchogenic carcinoma (1 paper, 2019). A lung carcinoma arising from the bronchial epithelium. "It has been reported that 79% of NSCLC cell lines lack Caspase-8, about 35% of SCLC and 18% of bronchogenic carcinoma have promoter methylation of CASP8." (PMID 31905767, 2019).
carcinoids (1 paper, 2015). "ASCL1 (p = 0.0016), BCL2 (p < 0.0001), CASP8 (p = 0.0030), CCNE1 (p = 0.0135), CDK1 (p = 0.0146), CDK2 (p = 0.0114), CDKN1A (p = 0.0107) and CDKN2A (p = 0.0002) showed lower expression in carcinoids compared to carcinomas." (PMID 26008974, 2015).
carpal tunnel syndrome (1 paper, 2022). Entrapment of the median nerve in the wrist that is characterized by numbness, tingling and painful movement. "Incidence of carpal tunnel syndrome in relation to quartiles of caspase-3, caspase-8 and HSP27." (PMID 35310100, 2022).
cervical squamous cell carcinoma (1 paper, 2019). A squamous cell carcinoma arising from the cervical epithelium. "Here, we report the association of Polo-like kinase (PLK) 3 expression and Caspase 8 T273 phosphorylation levels with survival among patients with cervical squamous cell carcinoma (CSCC) treated with CRT plus BT." (PMID 31475104, 2019).
cervical tumor (1 paper, 2022). "Therefore, Caspase-8 expression could be a marker in chemoresistant cervical tumors, suggesting CDK9 inhibitor treatment for their sensitization to Cisplatin-based chemotherapy." (PMID 36399280, 2022).
Chlamydia infection (1 paper, 2019). "Because conflicting observations have been reported on the effect of Chlamydia infection on CASP8 activation downstream of death receptor ligation, we initially considered canonical necroptosis as a possible explanation for the death observed in TNF/CHX-treated infected cells." (PMID 30375511, 2019).
cholesteatoma (1 paper, 2015). A pathologic process characterized by the proliferation of keratinizing squamous epithelium resulting in the accumulation of keratin and cells in the middle ear and/or mastoid. "NOD1 and many proapoptotic caspase genes such as CASP1, CASP2, CASP8, and CASP9 were not altered in cholesteatoma." (PMID 25922834, 2015).
chorioamnionitis (1 paper, 2025). A morphologic finding indicating inflammation of the fetal sac membranes. "Similarly, in the chorioamnionitis-induced PTB rat model, LPS administration increased cerebral expression of inflammatory and apoptotic markers, such as IL-1β, TNF-α, RANK, and caspase-8." (PMID 41009000, 2025).
chronic kidney disease (1 paper, 2024). Impairment of the renal function secondary to chronic kidney damage persisting for three or more months. "Furocoumarins are one of the most promising agents in the alleviation of oxidative and inflammatory stress-induced pathophysiological morbidities including chronic kidney disease due to their ability to regulate the activity of CASP-3, CASP-8, CASP-9, and SOD." (PMID 38660689, 2024).
chronic myelomonocytic leukemia (1 paper, 2025). A myelodysplastic/myeloproliferative neoplasm which is characterized by persistent monocytosis, absence of a Philadelphia chromosome and BCR/ABL fusion gene, fewer than 20 percent blasts in the bone marrow and blood, myelodysplasia, and absence of PDGFRA or PDGFRB rearrangement. "Dandelion root extract (DRE) triggers caspase-8 activation in chronic myelomonocytic leukemia (CMML) cells, causing mitochondrial destabilization and cell death without harming normal peripheral blood mononuclear cells." (PMID 41573227, 2025).
cleft lip (1 paper, 2022). Congenital defect in the upper lip where the maxillary prominence fails to merge with the merged medial nasal prominences. "The aim of this study was to evaluate single nucleotide polymorphisms (SNPs) in FOS, CASP8 and MMP2 and to determine their SNP-SNP interactions with CRISPLD2 variants in the risk of nonsyndromic cleft lip with or without cleft palate (NSCL±P) in the Brazilian population." (PMID 36661544, 2022).
clubfoot (1 paper, 2024). The most common congenital deformation of the foot, occurring in 1 of 1,000 live births. "Initially, genes associatedwith clubfoot (PITX1, TBX4, HOXA9, HOXD10, HOXD12,HOXD13, HOXA9, TPM1, TPM2, COL9A1, FLNB, CASP8,CASP10, UTX, CHD1, RIPPLY2, CAND2, WNT7) werescreened for potential variants." (PMID 38952703, 2024).
common variable immunodeficiency (1 paper, 2022). "Finally, ALPS or ALPS-like features may also arise from the complementary effect of variants in CASP10 and in another non-FAS gene, such as CASP8 or TNFRSF13C (i.e., BAFF receptor, whose mutations are typically associated with common variable immunodeficiency, CVID)." (PMID 35059842, 2022).
corticotroph adenomas (1 paper, 2020). "The methylation levels of ESR1 and CASP8 in corticotropin-secreting adenomas are also increased compared with those of silent corticotroph adenomas." (PMID 33574795, 2020). "Furthermore, CASP8 has been suggested to affect the functional behavior of corticotroph adenomas, but the specific mechanisms remain unknown." (PMID 33574795, 2020).
cutaneous squamous cell carcinoma (1 paper, 2021). "Cutaneous squamous cell carcinomas from patients with recessive dystrophic epidermolysis bullosa (RDEB) were enriched with mutations affecting CASP8." (PMID 34272401, 2021). "Skin from patients with RDEB is chronically blistering and inflamed, likely explaining the selective pressure to accumulate CASP8 mutations in this subtype of cutaneous squamous cell carcinoma." (PMID 34272401, 2021).
cyst (1 paper, 2021). A sac-like closed membranous structure that may be empty or contain fluid or amorphous material. "Strikingly, the massive cyst phenotype, which was lost in JNK1/2/RIPK1LPC-KO mice, was fully restored in quadruple-knockout mice with an additional loss of Caspase-8." (PMID 33798093, 2021). "In line with this, additional Caspase-8 deletion and concomitant apoptosis inhibition restored cyst formation (JNK1/2/RIPK1/Casp-8LPC-KO mice)." (PMID 33798093, 2021). "While the additional deletion of Caspase-8 or Mlkl alone did not rescue the cyst phenotype in JNK1/2LPC-KO, additional deletion of Ripk1 prevented biliary cyst formation." (PMID 33798093, 2021). "This would also explain why single Caspase-8 or Mlkl ablation did not prevent the cyst phenotype seen in JNK1/2LPC-KO mice." (PMID 33798093, 2021).
delirium (1 paper, 2025). A disorder characterized by confusion; inattentiveness; disorientation; illusions; hallucinations; agitation; and in some instances autonomic nervous system overactivity. "There were eight protective genes (DHODH,DHRS7B,TOP1MT,CASP8,GFM1,CPT1B,TK2,GPD2), and four genes (SCP2,DMPK,GSTK1,SIRT3) that increased delirium risk, as shown inFigure 2, withp = 0.05 (dotted line); and false discovery rate (FDR) < 0.05 (red asterisks)." (PMID 41330563, 2025). "Our findings show that higher expression of 8 genes, includingDHODH,DHRS7B,TOP1MT,CASP8,GFM1,CPT1B,TK2, andGPD2, could decrease the risk of delirium." (PMID 41330563, 2025).
diabetic cardiomyopathy (1 paper, 2022). Diabetic cardiomyopathy is a disorder of the heart muscle in people with diabetes. "In conclusion, SCU may alleviate diabetic cardiomyopathy by upregulating the autophagy-related factors (Beclin-1, LC3-I, and LC3-II) and downregulating apoptosis-related factors (caspase-3, caspase-8, caspase-9, caspase-12, Bax, and Cyt-C) of cardiomyocytes." (PMID 35571612, 2022).